APC (APC regulator of Wnt signaling pathway)
Diseases named in the same sentence as APC in open-access papers (continued):
Sharing a sentence is not in itself a finding about the gene and the disease.
tumor (continued). "Moreover, previous studies have shown that well-characterized tumor suppressors, such as RASSF1A and APC, act to stabilize microtubule polymerization." (PMID 33475085, 2021). "The availability of organoids and spheroids may finally allow the study of downstream targets of somatostatin and IGF2 in I-NETs as well as the importance of candidate tumor genes like MIR1-2, RASSF1A, APC, or CDKN1B." (PMID 34680217, 2021). "Our results showed that acute oxidative distress modulates canonical and non-canonical Wnt signals depending on tumor-specific characteristics and probably on APC protein status." (PMID 34885156, 2021). "We further evaluated the protein levels YAP and p-YAP in 293 cells, which were not APC-mutant and not-tumor cells." (PMID 34298652, 2021). "Although the reactivation of altered APC has been accomplished in vitro and has demonstrated complete tumor regression, it has never been validated in clinical trials." (PMID 35141142, 2021). "In the results of survival analysis-stratified tumour mutation, IL-8 and LMR were significant prognostic factors in patients without APC mutation, but not in patients with APC mutation." (PMID 32488137, 2020). "Methylation analysis of the CpG island at the APC 1A promoter, responsible for the predominant APC isoform, was detected in 10/25 (40%) of tumours, a higher rate than previously reported in CRC, although there has been at least one recent report of higher APC promoter methylation in CRC." (PMID 33352971, 2020). "Thus, we postulate that future examination of these tumor-derived mutations will reveal increased genomic instability, but at a level compatible with viability, and provide further evidence that altered regulation of APC/CCdh1, either positive or negative, has pathophysiological consequences." (PMID 32345958, 2020). "This activity of RA is independent of the APC tumor suppressor and ubiquitination-dependent degradation of cytoplasmic β-CATENIN." (PMID 32976767, 2020). "While APC itself could drive the disassembly of checkpoint complexes and the consequent inactivation of the checkpoint, high level of UBE2C observed in tumor cells was likely to promote the process 25-27." (PMID 31942195, 2020). "The tumor-promoting mutations in CTNNB1 (β-catenin), APC, or AXIN genes are also absent in this cell line." (PMID 32601309, 2020). "We selected a KRAS and APC mutant organoid line which responded to MEK inhibition with a strong increase in Wnt activity and could establish viable tumours with a take rate of 100%." (PMID 31097693, 2019). "In contrast, Ghrelin treatment did not alter tumor incidence or size in APC-mutant mice or colon-26 tumor bearing mice." (PMID 31681567, 2019). "The resulting topology integrates centrally involved proteins of the common signaling pathways and generally accepted cancer drivers in CRC—such as APC, p53m, KRAS, DCC, TGFβR, PTEN and SMAD4 allowing a simplified view on the progression from normal cells to tumor cells (Table A2, Figure A8)." (PMID 31861874, 2019). "Like PTEN and Rb1, APC is a new and important tumor suppressor in neurons that normally suppresses their growth." (PMID 31024258, 2019). "Interestingly, in the tumor cells derived from this particular strain, a β-catenin/TCF luciferase reporter assay (TOP-FLASH) and co-immunoprecipitation of β-catenin and APC indicated intermediate activation of the Wnt/β-catenin pathway." (PMID 31614493, 2019). "Although APC/C has not been studied in the context of E1A cancer cell toxicity, it has been shown that E1A interacts with APC components such as CBP/P300 in the context of viral transformation and likely has similar effects in tumour cells, so this link needs to be further explored." (PMID 31817939, 2019). "A particularly intriguing finding was that APC restoration in these developed tumors rapidly induces cell differentiation and tumor regression, without tumor relapse." (PMID 29652830, 2018).
tumor (continued). "Remarkably, ectopic restoration of the WT APC led to cell death in both patient-derived cell models, regardless of the resistance mechanisms that emerged in the tumour during clinical treatment." (PMID 29895949, 2018). "For example, intestinal epithelial cells are dependent on exogenous Wnt in culture but constitutively active Wnt signaling, due to genomic aberrations in genes such as APC and/or CTNNB1, often confers tumor cells with the ability to survive culture in Wnt‐free culture media." (PMID 29569246, 2018). "Unlike PPARα and γ, which present both pro-tumor and anti-tumor effects in colorectal cancer, different experimental evidences showed the pro-tumorigenic role of PPARβ/δ, mainly through its involvement in the APC/β-catenin/K-Ras oncogenic pathway." (PMID 29966227, 2018). "Upon restoration of APC expression, tumours regressed and CRC cells underwent differentiation toward normal intestinal cell types, thereby reinstating crypt–villus homeostasis." (PMID 30209039, 2018). "Mouse studies have demonstrated that the CBC cells are not alone in their tumor-generating capacity: constitutive β-catenin activation in Bmi1-CreER qSCs or APC deletion in Krt19+ qSCs were both sufficient for tumorigenesis." (PMID 30171151, 2018). "MiR-135b as an oncogene also targets different tumor suppressors such as LATS1–2 and APC." (PMID 30579343, 2018). "Based on the Circos plot analysis, stage III and IV tumor samples were associated with the absence(negative) of APC protein expression, whereas Y622* and Q625* mutations were associated with stage II, III and IV tumor samples." (PMID 28576136, 2017). "In the present study, APC was found to be frequently methylated in tumors, tumor-adjacent and tumor-distant tissues from breast cancer patients, but not in normal breast tissues from healthy women." (PMID 28403857, 2017). "For the following genes, a correlation was found between the methylation levels in tumors and those in tumor-adjacent tissues: CDKN2A (promoter) (r = 0.927, p < 0.001); BRCA1 (r = 0.878, p < 0.001); APC (r = 0.706, p = 0.001), ESR1 (r = 0.545, p = 0.019) and ESR2 (r = 0.543, p = 0.024)." (PMID 28403857, 2017). "Sixteen primary matched tumor and serum were analyzed by quantitative methylation specific PCR (QMSP) to determine analytical and clinical sensitivity of the genes tested (SSBP2, MCAM, ERα, ERβ, APC, CCND2, MGMT, GSTP1, p16 and RARβ2)." (PMID 28147335, 2017). "In tumor adjacent tissues, the promoter methylation status of ESR2 correlated with that of MGMT (r = 0.704, p = 0.002) and in tumor-distant tissues, the methylation status of APC correlated with that of ABCB1 (r = 0.756, p < 0.001)." (PMID 28403857, 2017). "APC and HIN1 are candidate tumor suppressors thought to be involved in breast carcinogenesis." (PMID 28222775, 2017). "Sodium bisulfite sequencing (BSP) was used to validate the 6 randomly selected candidate islands, in which the results of 5 mapped genes (ANKRD45, CDX1, APC, HOXD3 and TUBB6) showed significant differences in the 10 pairs of validation tumor and adjacent tissue cohorts." (PMID 28418032, 2017). "The methylation statuses of P16, RASSF1A, APC, RARβ, DAPK, CDH13, and MGMT were not linked to age, gender, smoking behavior, and tumor stage and histology in NSCLC." (PMID 28404957, 2017).
tumor (continued). "The present study provides methylation levels for the promoters of APC, BRCA1, CDKN2A, ESR1, ESR2, HER2/neu and PTEN, CDKN2A exon 2 and LINE-1 in tumor, tumor-adjacent and tumor-distant tissues from 18 breast cancer patients and normal breast tissues from four healthy women." (PMID 28403857, 2017). "Multivariate Cox proportional hazards regression analysis was performed to investigate the independent effects of methylated APC and RASSF1A promoter status on OS, adjusting for patients’ gender, age, clinical stage, tumor differentiation, lymph node status, CEA and CA199 levels." (PMID 28187169, 2017). "Activation of their protein products is a consequence of improper mitosis and leads to inhibition of the anaphase-promoting complex/cyclosome (APC/C, not to be confused with the APC tumor suppressor) and subsequent cell cycle arrest." (PMID 27276710, 2016). "While in shAPC-HCT116 tumors, since the APC did not act normally in the degradation of β-catenin, the elevated β-catenin played as a transcriptional factor and eventually promoted the tumor growth." (PMID 26760960, 2016). "Interestingly, the CtBP corepressor protein also co-ordinately regulates cell survival and EMT genetic programs, and is a target of several known tumor suppressors including HIPK2, Ink4a/Arf, and APC." (PMID 27655370, 2016). "Employing an APC-mutant mouse model (APCMin/+) the present study aimed to investigate the status of RXRα, an APC-independent factor involved in targeting β-catenin to UPP for degradation, in tumor-bearing and tumor-free areas of intestine after exposure to energetic 56Fe ions." (PMID 26500891, 2015). "Overall, MSI-H tumors showed a significantly higher incidence of indel mutations involving homopolymer regions (0.45 vs. 0.19 per tumor), especially in the PTEN gene (0.28 vs. 0 per tumor, P < 0.001), but not in the APC gene (0.17 vs. 0.16 per tumor)." (PMID 26517354, 2015). "Eleven cancer related genes were found to have methylation (defined as more than 10 % methylation) in at least some of the tumours: RASSF1A (64 %), TWIST1 (61 %), CDH13 (51 %), APC (50 %), MAL (35 %), GSTP1 (30 %), WIF1 (26 %), RARβ (19 %), BRCA1 (2 %), CDKN2A (2 %) and TP73 (2 %)." (PMID 26452468, 2015). "Further, while tumor cells do not effectively target βcat for destruction, it is less clear at what step destruction is blocked by APC truncation." (PMID 26393419, 2015). "In addition, the methylation level of the APC promoter is correlated with the age at the time of HCC diagnosis and the tumor size." (PMID 24765201, 2014). "Given that GRP78 has been reported to be secreted from solid tumor cells into the tumor microenvironment, we speculated that GRP78 secretion may lead to the extracellular release and cytosolic downregulation of APC protein." (PMID 24977433, 2014). "Another study analyzed whole blood samples from 76 CRPC patients, treated by maximum androgen blockage, in order to detect circulating tumor cells (CTCs) and methylated DNA (using qMSP) for a five-gene candidate marker panel (GSTP1, APC, PTGS2, MDR1 and RASSF1A)." (PMID 25238417, 2014). "The data indicated that the levels of the APC promoter were higher in 45 out of 57 (78.95%) tumor tissues compared with adjacent non-cancerous liver tissues." (PMID 24765201, 2014).
tumor (continued). "From the Human Tumor Metastasis RT-PCR array with ATAD2 siRNA-treated cells, we identified APC, ITGB3, FXYD5, ITGA7 and CTNNA1 (α-catenin), which are related to cell adhesion; among these, the expression of APC and CTNNA1 changed by at least 3-fold." (PMID 24552534, 2014). "In donor 95, APC was downregulated significantly in tumor versus nontumor (p < 0.003, t test, df = 4) but only by 30% versus normal liver controls." (PMID 23540693, 2013). "APC/β-catenin-rich complexes were observed at protrusion ends of migratory epithelial cells treated with a proteasome inhibitor or when EMT has been induced and in tumor cells with a mesenchymal, spindle-like morphology." (PMID 23302090, 2013). "Depletion of APC in these cells suppressed tumor cell migration but did not significantly impact proliferation." (PMID 23302090, 2013). "If APC is necessary (but not sufficient) for mitosis, and if there is enough residual APC function in a tumor, one would expect more frequent mitoses (but not a greater rate of mitosis) when WNT signaling is also upregulated." (PMID 24224156, 2013). "By Spearman correlation test, eight genes (AIM1, CCNA1, MCAM, PGP9.5, hMLH1, ARF, VGF and APC) showed to be independent of each other and were selected to be included in a logistic regression model, which predict the probability of tumour." (PMID 22068818, 2012). "Tumor samples from 155 patients with stages IIIB to IV NSCLC who received EGFR-TKI therapy were analyzed for DNA methylation status of Wnt antagonist genes, including SFRP1, SFRP2, SFRP5, DKK3, WIF1, and APC, using methylation specific PCR (MSP) method." (PMID 23009178, 2012). "Activation of APC by Cdc20 triggers chromosome segregation by ubiquitination of securin and cyclin B. Dysfunction of the SAC leads to aneuploidy and its reliable function is important for tumor suppression." (PMID 23071525, 2012). "Here, our observations show that the expression of DACT1 enhances cellular proliferation and promotes tumor growth and metastasis in the SW480, HCT116, LoVo and HT29 cell lines with or without APC or β-catenin mutations." (PMID 22470507, 2012). "Having ruled out direct APC mutations, we focused on potential APC-activating mutations of the β-catenin gene CTNNB1, which have been identified as a frequent event in various tumour entities." (PMID 22919349, 2012). "In accordance with the tumour suppressor gene model, a high percentage of the FAP-associated desmoids showed loss of region 5q22.2, containing the APC gene, which was very infrequently seen in the non-FAP associated tumours." (PMID 21931686, 2011). "There was a significant but weak positive correlation between APC and RASSF1A methylation levels, suggesting that tumours with high levels of APC methylation density frequently demonstrate high RASSF1A methylation levels (Pearson's correlation 0.301, p = 0.022)." (PMID 20208994, 2010). "Hypermethylation of promoter 1A has been readily demonstrated in various human tumours; however to our knowledge there is no or little evidence suggesting epigenetic inactivation of the APC promoter 1B through hypermethylation." (PMID 20208994, 2010).
tumor (continued). "Since APC is ranked as the 24th most significantly upregulated gene by clorgyline in the SAM procedure, and it is a well-known tumor suppressor that downregulates the activity of the beta-catenin pathway through various mechanisms, we validated its expression by qRT-PCR." (PMID 19691856, 2009). "In tumour cells lacking APC function, this homoeostatic loop fails to complete, leading to sustained expression and establishment of alternative Wnt-response pathways." (PMID 18414471, 2008). "As many cancer-related genes have been linked to the development of polyploidy, for example MYC, APC, Pim-1, BRCA2, and Aurora-A, our model may reflect an actual pathway for tumor initiation." (PMID 18596907, 2008). "The frequency of the methylation in tumour tissue was 57.1% in p16, 2.4% in DAP-kinase, 23.8% in GSTP1, 90.5% in APC, 45.2% in RIZ1, 64.3% in SFRP1, 59.5% in SFRP2, 28.6% in SFRP5, 47.6% in RUNX3, and 54.8% in SOCS1, while in MGMT, no aberrant methylation was detected." (PMID 17968429, 2007). "APC methylation was found to be statistically significantly different only when paired tumor and non-tumor lung samples were compared." (PMID 17967182, 2007). "The genes APC, MGMT; ER, GSTP1, DAPK, RARβ, FHIT and p16 were evaluated pre and post-treatment for DNA promoter methylation and gene expression by MSP (Methylation-Specific PCR) and RT-PCR respectively in each of the tumor samples." (PMID 15862127, 2005). "APC expression is similar between tumor and non-tumorous tissues." (PMID 40943055, 2025). "Moreover, the tumor-promoting role of miR-155-5p was also observed in FAP patients vs non-FAP controls, where a significant downregulation of miR-155-5p expression was found in FAP patients and APC and β-catenin mutant colorectal cancer cell lines." (PMID 40535722, 2025). "However, when APC loss was combined with NFKBIA deletion, constitutive NF-κB activation mimics inflammatory signaling, enabling non-stem cells to acquire tumor-initiating potential." (PMID 41002429, 2025). "Then, the collected tumor tissues were tested and verified by IHC experiments, and the results exhibited that after circ_0008126 overexpression, the levels of vimentin, ki-67, and PCNA proteins had been down-regulated, while the levels of APC and E-cadherin proteins had been upregulated." (PMID 39858034, 2025). "Consequently, inflammation in the distal colon may have triggered APC LOH, promoting tumor development." (PMID 41285904, 2025). "The mechanisms underlying why biallelic APC-mutant cells often do not progress to detectable cancers, and the precise stage at which “just-right” WNT signaling favors tumor progression, remain unclear." (PMID 41091816, 2025). "For instance, a stop gained variant was detected in the APC gene in plasma samples from M01 and a missense variant was detected in SMAD4 in plasma samples from patient M25, neither of which were detected in matched tumor tissue." (PMID 41044171, 2025). "Beyond its canonical role, APC also exerts non-Wnt functions that contribute to its tumor-suppressive capacity, including maintenance of chromosomal stability, regulation of microtubule dynamics, DNA repair, cell adhesion, and modulation of the tumor microenvironment (TME)." (PMID 41228231, 2025). "Competitive behavior promoting tumor development has been well documented in the intestine, where oncogenic mutations in APC, KRAS, or PIK3CA facilitate tumorigenesis through both tumor cell-intrinsic effects on cell growth and non-cell-autonomous effects on neighboring cells." (PMID 37832945, 2024).